AQP4 (aquaporin 4)
Diseases named in the same sentence as AQP4 in open-access papers (continued):
Sharing a sentence is not in itself a finding about the gene and the disease.
ischemic stroke (continued). "Research has indicated that mice without AQP4 exhibit enhanced neurological recovery and decreased brain swelling after experiencing a focal ischemic stroke." (PMID 39619615, 2024). "Resveratrol was demonstrated to reduce AQP4 expression in astrocytes, and SUR1 expression in endothelial cells after ischemic stroke." (PMID 34987407, 2021). "On the contrary, patients who had suffered a previous hemorrhagic stroke presented significantly lower levels of AQP4, whereas presenting a previous ischemic stroke did not result in changes in serum AQP4 levels." (PMID 33801197, 2021). "The increase in AQP4 expression is in agreement with the increased cerebral water contents in Zone D; the decrease in GFAP expression corresponds to the finding that astrocytes in the infarct core are disrupted in ischemic stroke." (PMID 32985231, 2020). "Altogether, the present study clearly demonstrates the benefits of a singular AQP4 inhibition in the treatment of ischemic stroke in a (for now) narrow therapeutic window." (PMID 29295526, 2017). "Shifting A1 to A2 reactivity, suppressing excessive AQP4 and Cx43 expression of astrocytes, and activating FGF2/PI3K/AKT pathway might be potential mechanisms of promoting neurovascular restoration with TMP after ischemic stroke." (PMID 37051111, 2023). "The results illustrated that the major transcellular proteins, Cav-1, Mfsd2a, and AQP4, have been changed and led to increasing transcellular permeability at the early stage of ischemic stroke, while the TJ proteins are not significantly altered or dysregulated." (PMID 35873558, 2022). "The data on the expression of aquaporin-4 in cerebral edema, particularly aquaporin-1 and aquaporin-4 that are expressed in the central nervous system and participate in the transport of water by the BBB, have been taken from several recent studies on extensive ischemic strokes." (PMID 35627746, 2022). "However, recently, researchers found that cerebrospinal fluid immediately flowed towards the brain parenchyma through the influx pathway of the glymphatic system after ischemic stroke, and an absence of AQP4 reduced the cerebrospinal fluid influx significantly." (PMID 35592320, 2022).
Alzheimer disease (105 papers, 2014 to 2026). A progressive, neurodegenerative disease characterized by loss of function and death of nerve cells in several areas of the brain leading to loss of cognitive function such as memory and language. "Post-mortem studies demonstrate that AQP4 mislocalization is strongly linked to Alzheimer’s disease (AD) pathology." (PMID 40746364, 2025). "Loss of AQP4 polarity has been implicated in Alzheimer’s disease, post-stroke cognitive impairment, and POCD." (PMID 40822471, 2025). "Loss of AQP4 polarity has been documented in Alzheimer’s disease, Parkinson’s disease, amyotrophic lateral sclerosis (ALS), chronic traumatic encephalopathy (CTE), and cerebral amyloid angiopathy, among others." (PMID 41373689, 2025). "Changes in levels of AQP1 and AQP4 expression were associated with the accumulation of amyloid beta in the brain of people with Alzheimer’s disease and PD." (PMID 41026459, 2025). "Aquaporin-4 (AQP4) is implicated in Alzheimer's disease (AD) pathology through its role in astrocytic function, cerebrovascular integrity, and beta-amyloid (Aβ) clearance." (PMID 40987419, 2025). "AQP4 has also been linked to Alzheimer's disease pathogenesis and suggested as important in the clearance of beta amyloid and tau." (PMID 34843700, 2022). "Changes in AQP4 expression and localization have been manifested in several CNS disorders, including traumatic brain injury, Alzheimer’s disease, chronic pain, and cognitive deficiency associated with diabetes." (PMID 35898407, 2022). "In the past, several reports of decreased peri-vascular AQP4 expression has been linked to neurodegenerative pathologies such as aging, cerebral small vessel disease and Alzheimer’s disease." (PMID 35248089, 2022). "For validating changes in gene expression, Vim, a pan-reactive marker expressed in disease-associated astrocytes in mouse models of Alzheimer’s disease, and Aqp4, the most prevalent water channel in CNS, were selected." (PMID 33980286, 2021). "The loss of perivascular AQP4 has been associated with increased amyloid-β burden in Alzheimer’s disease brain, following impaired clearance." (PMID 34148071, 2021). "Reactive astrogliosis, though common place in degenerative Alzheimer’s disease phenotypes, is associated with increased AQP4 expression, and reduced AQP4 polarization." (PMID 32705145, 2020). "The fact that neural hyperactivity precedes neurodegeneration is a common finding in Alzheimer’s disease and Aqp4 deficiency." (PMID 31190144, 2019). "The advantages and disadvantages of AQP4 neural tissue deficiency under pathological conditions, such as inflammation, and relationship with neural diseases, such as Alzheimer’s disease, have been previously reported." (PMID 31190144, 2019). "Loss of astrocyte polarity, in particular the loss of AQP4 in vasculature ensheathing astrocyte processes is another feature observed in animal models of Alzheimer’s disease, MS and NMO, which is considered to be a sign of impaired BBB integrity." (PMID 27941618, 2016). "A study of DTI along the perivascular space found decreased glymphatic function in PD patients compared to healthy controls, and several other studies have associated decreased AQP4 expression and polarization on astrocytes with other neurodegenerative diseases such as Alzheimer’s disease." (PMID 40429998, 2025). "In fact, dysfunction of AQP4 have been implicated in the pathogenesis of many degenerative disorders, including Alzheimer’s disease (AD), vascular cognitive impairment, idiopathic normal-pressure hydrocephalus, Parkinson’s disease dementia, frontotemporal dementia and Creutzfeldt-Jakob disease." (PMID 36688175, 2022). "Interestingly, disrupted perivascular AQP4 polarization caused by reactive astrogliosis was shown to impair glymphatic clearance in the models of Alzheimer disease and senescence." (PMID 32523952, 2020).
Alzheimer disease (continued). "Moreover, an array of studies have associated human AQP4 SNPs with neurological disorders including Alzheimer’s disease progression, vascular depression phenotype, leukariosis, outcome after traumatic head injury, edema formation, and the risk of stroke." (PMID 32369477, 2020). "Emerging data suggest that AQP4 may also be implicated in the glymphatic system and may be involved in the clearance of beta-amyloid in Alzheimer’s disease (AD)." (PMID 30691235, 2019). "Moreover, in the last five years, in five different studies, AQP4 has been found in association with EVs in CNS tissues in Alzheimer’s Disease (AD), stress-induced exhaustion disorder (SED), traumatic brain injury (reviewed here), suggesting the growing interest in these fields." (PMID 36071478, 2022). "Finally, AQP4 has been shown to have many roles in Alzheimer’s disease, including possibly mediating the clearance of amyloid-β, and AQP4 deficiency leads to impaired learning and memory via disruption of both the glutamate transport pathway and K+ ion homeostasis." (PMID 32111087, 2020). "Moreover, it was shown recently that AQP4 polarization itself is associated with Alzheimer’s disease status, suggesting that impaired glymphatic clearance may play a role in rendering the ageing brain vulnerable to aberrant protein deposition." (PMID 32705145, 2020). "The AQP4‐mediated glymphatic system has been shown to play a critical role in the clearance of Aβ and Tau proteins in Alzheimer's disease, but its role in hematoma clearance following ICH has not yet been clearly elucidated." (PMID 39530196, 2025). "AQP4 impairment along with neurodegenerative pathologies occur in many brain diseases, such as cerebral infarction, Alzheimer’s disease, and traumatic brain injury (TBI)." (PMID 40012567, 2025). "Specifically in Alzheimer’s disease, impaired Ca2+ signaling in astrocytic endfeet and mislocalization of aquaporin-4 (AQP4) channels disrupt glymphatic clearance, thereby promoting amyloid-β accumulation and vascular dysfunction." (PMID 41009644, 2025). "High-intensity interval training has been shown to ameliorate Alzheimer’s disease pathology through enhancement of the glymphatic system via restoration of AQP4 polarization." (PMID 41465272, 2025). "There were 3 main clusters: The red area is cluster 1, which contained 20 keywords with core cluster terms such as Alzheimers-disease, amyloid-beta, aquaporin 4, and blood–brain barrier." (PMID 40587680, 2025). "In Alzheimer’s disease, decreased expression of AQP-4 leads to impaired clearance of misfolded proteins, resulting in neurotoxicity and cognitive decline." (PMID 39144708, 2024). "Numerous investigations have established a correlation between the aquaporin-4 depolarization and the pathological manifestations of Alzheimer’s disease." (PMID 39596378, 2024). "Research also shows polarized distribution of AQP4 in the cortical regions of healthy individuals, whereas in Alzheimer’s disease, AQP4 polarization is disrupted (AQP4 depolarization)." (PMID 39295943, 2024). "Given AQP4’s crucial role in the glymphatic system and potential implications for Alzheimer’s disease, future research should include this water channel." (PMID 37508938, 2023). "The atrophy rate in patients with anti-aquaporin-4 antibody-positive NMOSD (AQP4 + NMOSD) was compared with age-sex-matched HCs recruited from the Japanese Alzheimer’s Disease Neuroimaging Initiative study and another study performed at Chiba University." (PMID 37537208, 2023). "Recently, a human study using MRI methods showed that the glymphatic system, which usually AQP4 is considered to belong to, does mediate cognitive dysfunction in Alzheimer’s disease." (PMID 36831830, 2023). "Polarized AQP4 at the endfoot of astrocytes is a key characteristic of the healthy CNS, as in Alzheimer's disease, AQP4 becomes more depolarized." (PMID 38077948, 2023).
Alzheimer disease (continued). "In Alzheimer’s disease (AD), AQP4 loses its normal location and thus reduces the clearance of amyloid-β plaques and tau protein." (PMID 36819717, 2023). "Studies have indicated that β-hydroxybutyrate (BHB) can raise the expression of SNTA1 and thus restoring AQP4 polarity in mice models with Alzheimer’s disease." (PMID 35898407, 2022). "It is notable that lower AQP4 expression was also observed in CSF from patients with Alzheimer's disease and Optic Neuromyelitis." (PMID 35401278, 2022). "Studies have indicated that BHB can raise the expression of SNTA1 and thus restoring AQP4 polarity in mice models with Alzheimer’s disease." (PMID 35898407, 2022). "It addresses the role of AQP4 in this system, its suggested roles in Aβ and tau clearance, and potential as a therapeutic target for Alzheimer’s Disease, as well as other AQP4-related neuropathologies." (PMID 33499944, 2021). "This review provides important and updated knowledge about glymphatic system, AQP4 itself, and their link with Alzheimer’s disease." (PMID 33499944, 2021). "Studies have shown alterations of perivascular AQP4 expression in idiopathic normal pressure hydrocephalus (iNPH) and Alzheimer’s disease (AD)." (PMID 34597351, 2021). "Aquaporin-4 water channels (AQP4) are an integral part of this system and related to neuropathologies, such as Alzheimer’s disease (AD)." (PMID 33499944, 2021). "We propose AQP4 as an interesting therapeutic target for Alzheimer’s disease, due to its plausible effects in Aβ and tau clearance and ameliorating of neuronal function, making it a target of enormous relevance to the field of ageing and neurodegeneration." (PMID 33499944, 2021). "Glymphatic clearance is impaired in a rodent animal model of Alzheimer’s disease, due to changes in the number of AQP4 water channels responsible for the movement of CSF and ISF, expressed on astrocytic endfeet." (PMID 33212927, 2020). "We observed here that AQP4 mRNA and protein expression levels are increased in the brains of rTg4510 mice, which is consistent with data from other degenerative Alzheimer’s disease scenarios." (PMID 32705145, 2020). "Taken together with similar findings in an amyloid-β model, in aged mice, and also in human Alzheimer’s disease, this research points to AQP4 as a novel therapeutic target for Alzheimer’s disease." (PMID 32705145, 2020). "While deletion of AQP4 is shown to reduce amyloid-β (Aβ) clearance and exacerbate Aβ peptide accumulation in plaques and vessels of Alzheimer’s disease mouse models, the mechanism and clearing pathways involved are debated." (PMID 32783141, 2020). "Our data suggest a role for AQP4-mediated clearance of tau from the brain, which therefore implies its importance in neurodegenerative tauopathies such as Alzheimer’s disease." (PMID 32705145, 2020). "A recent study showed elevated expression of AQP4 in the grey matter from autopsied temporal lobes from eight patients with Alzheimer’s disease (AD)." (PMID 32059400, 2020). "The emerging roles that AQP4 plays in brain clearance pathways point to AQP4 as a novel imaging target for neurological conditions such as Alzheimer's Disease." (PMID 30557661, 2019). "Here we review the latest findings related to aging and Alzheimer’s disease (AD) on this topic, as well as the available knowledge on pharmacological tools to target AQP-4." (PMID 32063858, 2019). "Redistribution of the water channel aquaporin-4 (AQP4) away from astrocyte endfeet and into parenchymal processes is a striking histological feature in mouse models of Alzheimer’s disease (AD) and other neurological conditions with prominent astrogliosis." (PMID 31068220, 2019). "The aberrant changes of AQP1 and AQP4 have been repeatedly observed in the brains of Alzheimer disease (AD)." (PMID 31814527, 2019).
Alzheimer disease (continued). "The astrocyte AQP4 polarized distribution-mediated glymphatic system is essential for amyloid-β and abnormal tau clearance and represents a potential therapeutic target for Alzheimer’s disease." (PMID 41465272, 2025). "AQP4 holds great potential as a therapeutic target for Alzheimer’s disease, with drug development and lifestyle interventions, such as aerobic exercise and dietary regulation, being promising approaches to restore AQP4 polarity and enhance its metabolic waste (i.e., β-amyloid) clearance capacity." (PMID 41465272, 2025). "This hypothesis was evident in a mouse Alzheimer’s disease (AD) model, in which deletion of Aqp4 sharply increased both Aβ plaque formation and cognitive deficits." (PMID 39226105, 2024). "Recent research has indicated that the disruption of the location of perivascular aquaporin-4 in neurodegenerative diseases, such as Alzheimer’s disease, could contribute to the increased vulnerability of the aging brain to protein misaggregation." (PMID 39596378, 2024). "In this study, longitudinal brain atrophy was compared in patients with AQP4 + NMOSD to age-sex-matched HCs using magnetic resonance imaging (MRI) images obtained from the Japanese Alzheimer’s Disease Neuroimaging Initiative (J-ADNI) study and another study performed at Chiba University." (PMID 37537208, 2023). "AQP4 levels are increased in Alzheimer ́s Disease in human samples." (PMID 36859364, 2023). "Interestingly, a comparative analysis of AQP4 in the CSF of Alzheimer’s disease patients and healthy controls revealed a 1.7× increase in AQP4, which positively correlated with tau levels." (PMID 36768495, 2023). "In a post-mortemcase series, reducedperivascular AQP4 abundance was observed in the frontal cortex of subjectsdiagnosed with Alzheimer’s disease, while preservation of perivascularAQP4 abundance was observed in subjects remaining cognitively intact over theage of 85." (PMID 34499128, 2022). "In Alzheimer's disease, AQP4 expression was reduced or even lost around amyloid β deposits." (PMID 36119130, 2022). "Owing to the loss of AQP4 in the tumor area, the exchange of CSF and ISF is decreased and the clearance of harmful solutes is limited in tumors, which has been confirmed in both Alzheimer’s disease and Parkinson’s disease." (PMID 35083148, 2021). "Finally, AQP4 as a therapeutic target is proposed to ameliorate Alzheimer’s Disease and other neuropathologies AQP4-related." (PMID 33499944, 2021). "Given that SNPs associated with the HtMi variant affect the cognitive decline in Alzheimer’s patients, the here described modulation of sleep intensity by the AQP4 haplotype provides a tantalizing link between Alzheimer’s disease, sleep intensity, and AQP4 in humans." (PMID 32369477, 2020). "AQP4 may mediate the clearance of amyloid beta peptides related to Alzheimer’s disease and regulate extracellular space volume during synaptic activity." (PMID 31190144, 2019). "AQP4 is upregulated and redistributed in reactive astrocytes, and becomes prominently expressed in parenchymal astrocyte processes in rodent models of many neurological diseases including Alzheimer’s Disease (AD)." (PMID 31068220, 2019). "The emerging importance of AQP4-mediated clearance pathways, such as the glymphatic system, make this technique a promising and clinically applicable tool for better understanding the role of AQP4-mediated clearance in pathological conditions like Alzheimer's Disease." (PMID 30557661, 2019). "The aberrant changes of AQP1 and AQP4 have been observed in the brains of Alzheimer disease (AD)." (PMID 31814527, 2019). "Moreover, several lines of evidences show that AQP4 expression level and localization are altered in Alzheimer's disease although initially differences have been noted in the reports of expression levels." (PMID 29888263, 2018).